DERL3 (derlin 3)
Description:
Functional component of endoplasmic reticulum-associated degradation (ERAD) for misfolded lumenal glycoproteins, but not that of misfolded nonglycoproteins. May act by forming a channel that allows the retrotranslocation of misfolded glycoproteins into the cytosol where they are ubiquitinated and degraded by the proteasome. May mediate the interaction between VCP and the misfolded glycoproteins. May be involved in endoplasmic reticulum stress-induced pre-emptive quality control, a mechanism that selectively attenuates the translocation of newly synthesized proteins into the endoplasmic reticulum and reroutes them to the cytosol for proteasomal degradation.
Synonyms: C22orf14; LLN2; FLJ43842; MGC71803; derlin-3; IZP6
Tractability: Antibody: UniProt predicts a signal peptide or a membrane-spanning region.
Gene: Protein-coding gene on chromosome 22 (23,834,503 to 23,839,128, reverse strand). Ensembl gene ENSG00000099958.
Subcellular location: Endoplasmic reticulum membrane
Subcellular location (Human Protein Atlas): Vesicles
Pathways (Reactome):
Disease: Defective CFTR causes cystic fibrosis
Immune System: AMPK-induced ERAD and lysosome mediated degradation of PD-L1(CD274)
Transport of small molecules: ABC-family protein mediated transport
Gene Ontology:
Molecular function: protein binding; protein-containing complex binding; signal recognition particle binding
Biological process: endoplasmic reticulum unfolded protein response; ERAD pathway; negative regulation of retrograde protein transport, ER to cytosol; protein N-linked glycosylation; ubiquitin-dependent protein catabolic process
Cellular component: endoplasmic reticulum membrane; endoplasmic reticulum
Genetic constraint (gnomAD): Loss-of-function variants: 22 observed, 22.22 expected, observed/expected ratio (o/e) 0.99, 90% interval 0.71 to 1.41. The upper end of that interval is the gene's LOEUF score, 1.41, which puts it in group 5 of 6, group 1 being the genes least tolerant of losing a copy. Missense variants: 319 observed, 279.09 expected, observed/expected ratio (o/e) 1.14, 90% interval 1.04 to 1.25. Synonymous variants: 145 observed, 122.54 expected, observed/expected ratio (o/e) 1.18, 90% interval 1.03 to 1.36.
Homologues: Orthologues: chimpanzee DERL3 (98% identical), macaque DERL3 (98% identical), guinea pig DERL3 (96% identical), dog DERL3 (94% identical), pig DERL3 (94% identical), rabbit DERL3 (94% identical), mouse Derl3 (88% identical), zebrafish derl3 (75% identical), rat Derl3 (66% identical), Caenorhabditis elegans der-2 (59% identical), Drosophila melanogaster Der-2 (58% identical). Paralogues in human: DERL2 (76% identical), DERL1 (33% identical).